GRIK3 (glutamate ionotropic receptor kainate type subunit 3)
Description:
Ionotropic glutamate receptor that functions as a cation-permeable ligand-gated ion channel, gated by L-glutamate and the glutamatergic agonist kainic acid. Binding of the excitatory neurotransmitter L-glutamate induces a conformation change, leading to the opening of the cation channel, and thereby converts the chemical signal to an electrical impulse. The receptor then desensitizes rapidly and enters a transient inactive state, characterized by the presence of bound agonist. In association with GRIK2, involved in presynaptic facilitation of glutamate release at hippocampal mossy fiber synapses (By similarity).
Synonyms: GluK3; EAA5; GluR7; GLR7; GluR7a
Tractability: Small molecule: an approved drug acts on it; it belongs to a druggable protein family. Antibody: its Gene Ontology location is reachable by antibodies, with high confidence; UniProt places it where antibodies can reach, with medium confidence; UniProt predicts a signal peptide or a membrane-spanning region. PROTAC: UniProt records ubiquitination sites on it; its protein half-life has been measured; a small molecule that binds it is known.
Target class: Ionotropic glutamate receptor; Kainate receptor; Ligand-gated ion channel; Ion channel
Safety:
Unwanted effects reported when the protein is acted on. In parentheses: how it was acted on, where the effect was seen, and who reports it.
extrapyramidal symptoms (source: ClinPGx)
Gene: Protein-coding gene on chromosome 1 (36,795,527 to 37,034,515, reverse strand). Ensembl gene ENSG00000163873.
Subcellular location: Cell membrane; Postsynaptic cell membrane
Pathways (Reactome):
Neuronal System: Activation of Ca-permeable Kainate Receptor; Presynaptic function of Kainate receptors
Gene Ontology:
Molecular function: adenylate cyclase inhibiting G protein-coupled glutamate receptor activity; glutamate-gated receptor activity; kainate selective glutamate receptor activity; glutamate receptor activity; transmitter-gated monoatomic ion channel activity involved in regulation of postsynaptic membrane potential; glutamate-gated calcium ion channel activity; ligand-gated monoatomic ion channel activity; ligand-gated monoatomic ion channel activity involved in regulation of presynaptic membrane potential; monoatomic ion channel activity; signaling receptor activity
Biological process: G protein-coupled glutamate receptor signaling pathway; glutamate receptor signaling pathway; regulation of membrane potential; modulation of chemical synaptic transmission; negative regulation of synaptic transmission, glutamatergic; synaptic transmission, glutamatergic; adenylate cyclase-inhibiting G protein-coupled glutamate receptor signaling pathway; calcium-mediated signaling; ionotropic glutamate receptor signaling pathway; monoatomic ion transmembrane transport; monoatomic ion transport; regulation of postsynaptic membrane potential; regulation of presynaptic membrane potential
Cellular component: plasma membrane; axon; dendrite; dendrite cytoplasm; glutamatergic synapse; kainate selective glutamate receptor complex; perikaryon; postsynaptic density membrane; postsynaptic membrane; presynaptic membrane; terminal bouton; membrane
Genetic constraint (gnomAD): Loss-of-function variants: 21 observed, 76.31 expected, observed/expected ratio (o/e) 0.28, 90% interval 0.19 to 0.4. The upper end of that interval is the gene's LOEUF score, 0.4, which puts it in group 1 of 6, group 1 being the genes least tolerant of losing a copy. Missense variants: 761 observed, 1,086.4 expected, observed/expected ratio (o/e) 0.7, 90% interval 0.66 to 0.74. Synonymous variants: 440 observed, 452.41 expected, observed/expected ratio (o/e) 0.97, 90% interval 0.9 to 1.05.
Homologues: Orthologues: chimpanzee GRIK3 (99% identical), macaque GRIK3 (99% identical), dog GRIK3 (99% identical), pig GRIK3 (99% identical), mouse Grik3 (99% identical), guinea pig GRIK3 (95% identical), rabbit GRIK3 (94% identical), rat Grik3 (93% identical), tropical clawed frog grik3 (85% identical), zebrafish grik3 (75% identical), Drosophila melanogaster CG11155 (43% identical), Drosophila melanogaster Ekar (37% identical), and 37 more. Paralogues in human: GRIK2 (78% identical), GRIK1 (72% identical), GRIK5 (42% identical), GRIK4 (40% identical), GRIA2 (37% identical), GRIA1 (36% identical), GRIA4 (36% identical), GRIA3 (35% identical), GRID1 (29% identical), GRID2 (28% identical), GRIN1 (23% identical), GRIN2A (22% identical), and 5 more.